SNORD121A (small nucleolar RNA, C/D box 121A)
Gene: Small nucleolar RNA gene on chromosome 9 (33,952,769 to 33,952,850, reverse strand). Ensembl gene ENSG00000238886.
Gene Ontology:
Biological process: RNA processing
Cellular component: nucleolus
Homologues: Orthologues: chimpanzee SNORD121A (99% identical), macaque SNORD121A (99% identical), dog SNORD121A (93% identical), guinea pig SNORD121A (93% identical), pig SNORD121A (90% identical), rabbit SNORD121A (89% identical), mouse Gm23090 (87% identical), rat Snord121a (87% identical), rat LOC120103358 (84% identical), mouse Gm24837 (82% identical). Paralogues in human: SNORD121B (66% identical).